NUFIP1 (nuclear FMR1 interacting protein 1)
Description:
Binds RNA.
Synonyms: NUFIP; Rsa1; bA540M5.1
Tractability: No criterion of Open Targets' tractability assessment is met for any kind of drug.
Gene: Protein-coding gene on chromosome 13 (44,939,249 to 44,989,471, reverse strand). Ensembl gene ENSG00000083635.
Subcellular location: Nucleus
Subcellular location (Human Protein Atlas): Nucleoplasm; Nucleoli
Gene Ontology:
Molecular function: ATPase binding; DNA binding; identical protein binding; protein binding; protein-macromolecule adaptor activity; RNA binding; snoRNA binding
Biological process: box C/D snoRNP assembly; positive regulation of transcription by RNA polymerase II; RNA processing
Cellular component: nuclear matrix; nucleolus; nucleoplasm; perichromatin fibrils; pre-snoRNP complex; protein-containing complex; transcription elongation factor complex; presynaptic active zone; nucleus; synapse
Genetic constraint (gnomAD): Loss-of-function variants: 18 observed, 30.82 expected, observed/expected ratio (o/e) 0.58, 90% interval 0.4 to 0.87. The upper end of that interval is the gene's LOEUF score, 0.87, which puts it in group 3 of 6, group 1 being the genes least tolerant of losing a copy. Missense variants: 419 observed, 443.76 expected, observed/expected ratio (o/e) 0.94, 90% interval 0.87 to 1.02. Synonymous variants: 167 observed, 163.53 expected, observed/expected ratio (o/e) 1.02, 90% interval 0.9 to 1.16.
Homologues: Orthologues: chimpanzee NUFIP1 (99% identical), macaque NUFIP1 (96% identical), dog NUFIP1 (79% identical), rabbit NUFIP1 (79% identical), guinea pig NUFIP1 (78% identical), pig NUFIP1 (76% identical), mouse Nufip1 (71% identical), rat Nufip1 (69% identical), tropical clawed frog nufip1 (34% identical), zebrafish nufip1 (23% identical), Drosophila melanogaster Nufip (20% identical).
Diseases named in the same sentence as NUFIP1 in open-access papers:
NUFIP1 is named in the same sentence as 17 diseases in open-access papers, as found by Europe PMC text mining. Sharing a sentence is not in itself a finding about the gene and the disease. The quoted sentences say what the papers report.
neuroblastoma (3 papers, 2021 to 2022). Neuroblastoma (NB) is the most common solid, extracranial childhood tumor. "Mutations in NUFIP1 have been detected in neuroblastoma, and a fusion of NUFIP1 with ETV-6 has been identified in acute lymphoblastic leukemia." (PMID 34367967, 2021). "Mutated genes NUFIP1 had a higher level of expression in metastasis tumor than primary tumor in neuroblastoma indicating its oncogenic driver role." (PMID 34863153, 2021). "Large-scale transcriptome sequencing of metastatic neuroblastoma showed a mutation of NUFIP1 gene in tumor cells, in which the expression score of NUFIP-1 mutant alleles was greater than 30%, hinting that these mutant genes might have potential carcinogenic effects." (PMID 35414791, 2022).
Obesity (2 papers, 2012 to 2021). Accumulation of substantial excess body fat. "Homozygous loss of NUFIP1 may contribute to psychomotor delays, and NUFIP1 gene polymorphisms have been associated with osteoporosis and obesity-related traits." (PMID 34367967, 2021). "Among 5 selected polymorphisms (rs9594738 of RANKL, rs17066364 of NUFIP1, rs7227401 of OSBPL1A, and rs1856057 and rs2982573 of ESR1) analyzed, 2 polymorphisms (rs9594738 and rs17066364) were associated with obesity-related traits." (PMID 23300848, 2012). "Boys with fragile X syndrome exhibit a predisposition to increased obesity, although no linkage has been established between NUFIP1 and obesity." (PMID 23300848, 2012).
Sepsis (2 papers, 2025 to 2026). Sepsis is defined as life-threatening organ dysfunction caused by a dysregulated host response to infection. "Fifthly, while we corroborated the critical role of ZBP1 in NUFIP1-mediated ribophagy associated with CD4+ T lymphocytes’ PANoptosis in sepsis, the precise interactional dynamics and underlying molecular mechanisms between these proteins remain to be elucidated." (PMID 40995563, 2025). "Our previous studies demonstrated that nuclear fragile X mental retardation-interacting protein 1 (NUFIP1)-mediated ribophagy conferred cytoprotection against apoptosis in CD4+ T lymphocytes during sepsis, thereby preserving host immunocompetence." (PMID 40995563, 2025). "The impact of NUFIP1-mediated ribophagy on CD4+ T lymphocyte PANoptosis in sepsis was investigated by establishing a lentiviral transfection model in Jurkat T cells." (PMID 40995563, 2025). "In the current study, we found that NUFIP1-mediated ribophagy modulated CD4+ T lymphocyte PANoptosis in sepsis, consequently augmenting T cell-mediated immunity and preserving systemic immune homeostasis." (PMID 40995563, 2025). "Significant expression of the ribophagy-specific receptor NUFIP1 and autophagy-associated protein LC-3B was observed in CD4+ T lymphocytes after sepsis, with a corresponding decrease in the expression of ribosomal self-proteins ribosomal protein L7 (RPL7), RPL23, and RPL26." (PMID 40995563, 2025). "Combining the identified top 20 differentially expressed proteins and KEGG pathway enrichment analysis, it was inferred that the cGAS-STING signaling pathway might play a potential role in CD4+ T lymphocyte PANoptosis, regulated by NUFIP1-mediated ribophagy in sepsis." (PMID 40995563, 2025). "Integrating the recently proposed concept of PANoptosis and the concurrent existence of multiple interconnected PCD modes in immune cells, we hypothesize that NUFIP1-mediated ribophagy might play a regulatory role in PANoptosis of CD4+ T lymphocytes during sepsis." (PMID 40995563, 2025). "Next, Cd4creNufip1fl/fl mice were utilized to explore the influence of conditional NUFIP1 knockout on CD4+ T cell immune function, multi-organ damage, and prognosis in sepsis." (PMID 40995563, 2025). "Mechanistically, sepsis-induced ribosome collision activated the cGAS-STING signaling axis, which in turn recruited NUFIP1 to STING protein complexes." (PMID 40995563, 2025). "Notably, NUFIP1-mediated ribophagy of CD4+ T lymphocytes exhibited a significant impact on host immunosuppression status, multiple organ damage, and sepsis prognosis." (PMID 40995563, 2025). "We found that the levels of NUFIP1 and ZBP1 in the CD4+ T lymphocytes of septic patients significantly increased compared to those without sepsis, corresponding to experimental data in murine models, thereby underscoring their conserved biomarker potential for the diagnosis of sepsis." (PMID 40995563, 2025).
breast carcinoma (1 paper, 2022). "Seven genes were shared between prostate and positive breast cancer responders (TRNT1, NUFIP1, TDG, HSPA8, OTUD6B, RBM12, and DENND3)." (PMID 35520391, 2022).
cervical cancer (1 paper, 2021). A primary or metastatic malignant neoplasm involving the cervix. "However, the potential role of NUFIP1 in the process of cervical cancer development remains to be revealed." (PMID 34863153, 2021). "It is displayed in kaplan–Meier curves that higher expression level of EEF1D, CTU1, EIF3C, WDR43, NUFIP1, ZC3HAV1L and PRPF40B indicated a lower overall survival of cervical cancer patients." (PMID 34863153, 2021).
colorectal cancer (1 paper, 2021). A primary or metastatic malignant neoplasm that affects the colon or rectum. "NUFIP1 knockdown suppressed cell growth in the colorectal cancer cell lines HT-29 and HCT116 (*P < 0.05 vs. sh-Ctrl lentivirus)." (PMID 34367967, 2021). "We previously showed that NUFIP1 was upregulated in colorectal cancer (CRC), but how the protein may contribute to the disease and patient prognosis is unknown." (PMID 34367967, 2021).
Hypsarrhythmia (1 paper, 2022). Hypsarrhythmia is abnormal interictal high amplitude waves and a background of irregular spikes. "Diseases associated with NUFIP1 mutations include Peho Syndrome (progressive encephalopathy with Edema, Hypsarrhythmia and Optic atrophy), an autosomal recessive and dominate, progressive neurodegenerative disorder that starts in the first few weeks or months of life." (PMID 36163262, 2022).
tumor (3 papers, 2021 to 2022). "NUFIP1 knockdown significantly reduced tumor volume, signaling and weight in a xenograft nude mouse model (*P < 0.05 vs. sh-Ctrl lentivirus)." (PMID 34367967, 2021). "Our analyses of patient materials, cell lines and tumor xenografts suggest that NUFIP1 is an oncogene that drives tumor growth and progression in CRC." (PMID 34367967, 2021). "Knockdown of NUFIP1 significantly suppressed CRC tumor growth both in vivo and in vitro by suppressing cell proliferation and inducing cell apoptosis." (PMID 34367967, 2021). "UA treatment enhanced the anti-tumor effects of NUFIP1 knockdown, suggesting the potential of NUFIP1 as a diagnostic and prognostic marker, as well as therapeutic target in CRC." (PMID 34367967, 2021). "We also used in vitro and in vivo assays to investigate the effect of NUFIP1 knockdown on tumor growth." (PMID 34367967, 2021). "Moreover, our current study found that UA further enhanced the anti-tumor effects of NUFIP1 knockdown for the first time." (PMID 34367967, 2021). "DEP screening in HCT116 cells after NUFIP1 knockdown identified 136 overexpressed and 41 underexpressed proteins, with several of those DEPs (including E2F3, STAT1) involved in regulating tumor growth." (PMID 34367967, 2021). "Verification of NUFIP1 protein expression by IHC analysis in CRC TMA (including 71 pairs of CRC samples) indicated that NUFIP1 was expressed in CRC tissues at higher levels than in matched noncancerous tissue (P < 0.05, tumor vs. normal tissue)." (PMID 34367967, 2021). "Quantitative PCR analysis on a CRC cDNA chip (Shanghai Outdo Biotech, Shanghai, China) in 15 pairs of CRC patients’ samples confirmed that NUFIP1 mRNA expression was up-regulated in CRC tissues, compared with matched noncancerous colorectal tissues (P < 0.05, tumor vs. normal tissue)." (PMID 34367967, 2021).
cancer (2 papers, 2021). A tumor composed of atypical neoplastic, often pleomorphic cells that invade other tissues. "Few studies have examined a role for NUFIP1 in cancer, which encouraged us to assess its potential involvement in CRC." (PMID 34367967, 2021). "Moreover, NUFIP1, in addition to roles in diseases such as fragile X syndrome and cancers, is involved in numerous cellular processes and responses to various stresses." (PMID 34367967, 2021). "Moreover, we investigated the potential of NUFIP1 to be a therapeutic target in CRC by treating cancer cells with UA." (PMID 34367967, 2021). "In our work, overexpression of NUFIP1 in CRC tissues correlated with shorter survival and more advanced cancer stage." (PMID 34367967, 2021).
NUFIP1 also shares sentences with these, for which no sentence is quoted: acute lymphoblastic leukemia (2 papers); fragile X syndrome (1); optic atrophy (1); osteoporosis (1); PEHO syndrome (1); prostate adenocarcinoma (1); prostate carcinoma (1); prostate tumor (1).